DCBLD2 (discoidin, CUB and LCCL domain containing 2)
Synonyms: CLCP1; ESDN
Tractability: Antibody: its Gene Ontology location is reachable by antibodies, with high confidence; UniProt predicts a signal peptide or a membrane-spanning region; the Human Protein Atlas places it where antibodies can reach. PROTAC: ubiquitination databases record sites on it; its protein half-life has been measured.
Gene: Protein-coding gene on chromosome 3 (98,795,941 to 98,901,729, reverse strand). Ensembl gene ENSG00000057019.
Subcellular location: Membrane
Subcellular location (Human Protein Atlas): Cytosol; Plasma membrane; Golgi apparatus
Gene Ontology:
Molecular function: protein binding; signaling receptor activity
Biological process: negative regulation of cell growth; wound healing; intracellular receptor signaling pathway
Cellular component: cell surface; plasma membrane; membrane
Genetic constraint (gnomAD): Loss-of-function variants: 52 observed, 81.1 expected, observed/expected ratio (o/e) 0.64, 90% interval 0.51 to 0.81. The upper end of that interval is the gene's LOEUF score, 0.81, which puts it in group 3 of 6, group 1 being the genes least tolerant of losing a copy. Missense variants: 899 observed, 940.96 expected, observed/expected ratio (o/e) 0.96, 90% interval 0.9 to 1.01. Synonymous variants: 350 observed, 330.27 expected, observed/expected ratio (o/e) 1.06, 90% interval 0.97 to 1.16.
Homologues: Orthologues: chimpanzee DCBLD2 (99% identical), macaque DCBLD2 (98% identical), pig DCBLD2 (94% identical), dog DCBLD2 (92% identical), guinea pig DCBLD2 (89% identical), rabbit DCBLD2 (88% identical), rat Dcbld2 (85% identical), mouse Dcbld2 (84% identical), tropical clawed frog dcbld2 (63% identical), zebrafish dcbld2 (48% identical). Paralogues in human: NETO2 (14% identical), NETO1 (14% identical), NRP1 (13% identical), NRP2 (12% identical), CNTNAP2 (11% identical), CNTNAP5 (11% identical), CUBN (11% identical), NRXN3 (11% identical), CNTNAP4 (11% identical), NRXN1 (11% identical), F5 (11% identical), NRXN2 (11% identical), and 23 more.
Diseases named in the same sentence as DCBLD2 in open-access papers:
DCBLD2 is named in the same sentence as 34 diseases in open-access papers, as found by Europe PMC text mining. Sharing a sentence is not in itself a finding about the gene and the disease. The quoted sentences say what the papers report.
lung carcinoma (9 papers, 2008 to 2024). "DCBLD2 is overexpressed in glioblastoma, colorectal cancer, and lung cancer, and it is strongly associated with tumour migration and invasion." (PMID 32958051, 2020). "DCBLD2/ESDN is ubiquitously expressed but linked to metastasis formation since it has been cloned and found to be significantly up-regulated from highly metastatic lung cancer cells." (PMID 20525283, 2010). "Herein, we aimed to investigate the effect of MIR100HG on the proliferation and metastasis of lung cancer cells by mediating the miR‐5590‐3p/DCBLD2 axis." (PMID 38602284, 2024). "The novelty of this study is that MIR100HG promotes lung cancer progression by modulating the miR‐5590‐3p/DCBLD2 axis." (PMID 38602284, 2024). "DCBLD2 expression levels in lung cancer tissues and corresponding paracancerous normal tissues were examined by RT‐qPCR, and the findings revealed that DCBLD2 expression was notably upregulated in lung cancer tissues." (PMID 38602284, 2024). "Collectively, we highlighted that MIR100HG promoted lung cancer progression by targeting and negatively regulating DCBLD2 through binding with miR‐5590‐3p." (PMID 38602284, 2024). "RNA levels of MIR100HG, miR‐5590‐3p, and DCBLD2 in lung cancer tissues and cells were detected by quantitative reverse‐transcription polymerase chain reaction, and protein level was assessed by Western blot." (PMID 38602284, 2024). "LncRNA MIR100HG promotes lung cancer progression by targeting and negatively regulating DCBLD2 through binding with miR‐5590‐3p." (PMID 38602284, 2024). "MIR100HG and DCBLD2 were highly expressed, while miR‐5590‐3p was lowly expressed in lung cancer tissues and cells." (PMID 38602284, 2024). "In summary, the novelty of this study is that MIR100HG promotes lung cancer progression by modulating the miR‐5590‐3p/DCBLD2 axis." (PMID 38602284, 2024). "The aim of this paper is to investigate the effect of long noncoding RNA (lncRNA) MIR100HG on the proliferation and metastasis of lung cancer cells by mediating the microRNA (miR)−5590‐3p/DCBLD2 axis." (PMID 38602284, 2024). "Among the 17 significantly downregulated genes in the durable disease control group, DCBLD2 was reported as a potential poor prognostic marker in colorectal cancer and lung cancer by stimulation of epithelial-to-mesenchymal transition." (PMID 38339307, 2024). "Previous work demonstrated that the SEMA4B and DCBLD2 interaction is involved in the regulation of the motility of lung cancer cell lines." (PMID 34522794, 2021). "DCBLD2 is highly expressed by metastatic cells in culture, and in lung cancer tissue at both primary and metastatic sites." (PMID 20195492, 2010). "In lung cancer, DCBLD2 has been shown to be highly upregulated in the cell line NCI-H460-LNM35, in association with its acquisition of metastatic phenotype, and also upregulated in high frequency in metastatic lesions from lung cancers." (PMID 18827820, 2008). "Therefore, in this current research, we aimed to probe the impact of MIR100HG on the proliferation and metastasis of lung cancer cells by mediating the miR‐5590‐3p/DCBLD2 axis." (PMID 38602284, 2024). "DCBLD2 was also significantly upregulated in lung cancer cells compared with BEAS‐2B cells." (PMID 38602284, 2024). "Downregulation of miR‐5590‐3p partly overturned the suppressive effect of silencing MIR100HG on lung cancer cell proliferation and metastasis, and overexpression of DCBLD2 also reversed the effect of overexpression of miR‐5590‐3p on lung cancer cell proliferation and metastasis." (PMID 38602284, 2024). "Furthermore, it was demonstrated that the over-expression of DCBLD2 is related to the increased invasive capacity of cancer cells and poor prognosis of patients with lung cancer, gastric cancer, colorectal cancer, and pancreatic cancer." (PMID 36034778, 2022). "Besides, DCBLD2 has been revealed to participate in lung cancer development." (PMID 38602284, 2024).
lung carcinoma (continued). "Besides, downregulation of miR‐5590‐3p reversed the suppressive effect of silencing MIR100HG on lung cancer cell proliferation and metastasis, and overexpression of DCBLD2 also reversed the effect of overexpression of miR‐5590‐3p on lung cancer cell proliferation and metastasis." (PMID 38602284, 2024). "Besides, the downregulation of miR‐5590‐3p reversed the suppressive effect of silencing MIR100HG on lung cancer cell proliferation and metastasis, and the overexpression of DCBLD2 also reversed the effect of overexpression of miR‐5590‐3p on lung cancer cell proliferation and metastasis." (PMID 38602284, 2024). "It is also shown that DCBLD2 may play a role in cell motility, and thus it is suggested that this novel gene may become a target of therapy to inhibit metastasis of lung cancers." (PMID 18827820, 2008). "DCBLD2 has been reported to play a positive role in lung cancer and glioblastomas but shows a negative role in gastric and neuroendocrine cancers." (PMID 34721037, 2021).
colorectal cancer (8 papers, 2020 to 2024). A primary or metastatic malignant neoplasm that affects the colon or rectum. "DCBLD2 over-expression has been implicated in causing tumorigenesis, invasion and metastasis in colorectal cancer expression." (PMID 33976744, 2021). "In this study, the database and clinical sample verification results showed that DCBLD2 expression substantially higher in colorectal cancer tissues than in normal tissues, causing a poor prognosis." (PMID 34095137, 2021). "In colorectal cancer, high DCBLD2 expression is associated with poor patient survival, as well as tumorigenesis, invasion and metastasis of cancer cells." (PMID 33834039, 2021). "DCBLD2 was significantly expressed in colorectal cancer tumor tissues compared with the normal tissues." (PMID 34095137, 2021). "The result of the scratch experiment showed that the reduction of DCBLD2 expression would inhibit the migration ability of colorectal cancer cells, similar to the Transwell migration experiment." (PMID 34095137, 2021). "DCBLD2 expression is downregulated in colorectal cancer, gastric cancer, melanomas and neuroendocrine cancer." (PMID 33808696, 2021). "In this study, we elucidate the effect and mechanism of DCBLD2 on the degree of malignancy and 5-FU treatment sensitivity of colorectal cancer through in vivo and in vitro studies." (PMID 34095137, 2021). "Elevated expression of DCBLD2 was significantly associated with decreased OS time in various cancers including PDAC, colorectal cancer, hypopharyngeal squamous cell carcinoma and melanoma." (PMID 33834039, 2021). "Then, we down-regulated the mRNA level of DCBLD2 gene in colorectal cancer cells HCT116 and CACO-2, and found that its mRNA and protein level was further down-regulated." (PMID 34095137, 2021). "The results of in vitro and in vivo experiments showed that the inhibition of DCBLD2 reduced the proliferation, migration and invasion of colorectal cancer cells, inhibited the angiogenesis of endothelial cells, and enhanced the drug sensitivity to 5-FU." (PMID 34095137, 2021). "With regard to the mechanism of the effect of DCBLD2 on the development of colorectal cancer, our study proposed two independent mechanisms." (PMID 34095137, 2021). "In conclusion, we elucidate for the first time the potential role of DCBLD2 in 5-FU resistance in colorectal cancer." (PMID 34095137, 2021). "Immunohistochemical experiments of 16 colorectal cancer patient tissues showed a significant positive correlation between the expression of DCBLD2 and CD31 at the protein level." (PMID 34095137, 2021). "From the perspective of tumor microenvironment, we believe that the two mechanisms of the role of DCBLD2 in the occurrence and development of colorectal cancer are complementary and superimposed." (PMID 34095137, 2021). "We down-regulated the mRNA level of DCBLD2 in colorectal cancer cells (HCT116 and CACO-2)." (PMID 34095137, 2021). "The TCGA data analysis showed that the downstream DCBLD2 gene was enriched in the focal adhesion pathway in colorectal cancer, and DCBLD2 and the key signal factor ITGB1 of the focal adhesion pathway show a significant positive correlation in the mRNA expression level." (PMID 34095137, 2021). "For the second mechanism, we first used TCGA data to analyze the relationship between the expression of DCBLD2 gene and the activity of 10 well-known tumor-related pathways in patients with colorectal cancer, and found that this gene has the greatest impact on EMT and can activate this pathway." (PMID 34095137, 2021). "The mRNA level of DCBLD2 was downregulated in colorectal cancer cells (HCT116 and CACO-2)." (PMID 34095137, 2021). "We down-regulated the expression of DCBLD2 in colorectal cancer cells, and the mRNA and protein levels of transcription factors upstream of EMT signal, ZEB1, ZEB2 and SNAIL significantly decreased, which suppress epithelial genes and activate a mesenchymal expression program." (PMID 34095137, 2021).
colorectal cancer (continued). "DCBLD2 is highly expressed in various cancers, including colorectal cancer." (PMID 34095137, 2021). "Similarly, colorectal cancer patients were divided into the DCBLD2 high and low expression groups." (PMID 34095137, 2021). "CCK-8, clone formation, scratch, Transwell invasion and migration assays were used to assess DCBLD2 effects on the proliferation, metastasis, and 5-FU drug sensitivity on HCT116 and Caco-2 colorectal cancer cells." (PMID 34095137, 2021). "And our study found that DCBLD2 can promote EMT and angiogenesis, thus promoting the development of colorectal cancer." (PMID 34095137, 2021).
glioblastoma (7 papers, 2015 to 2022). The most malignant astrocytic tumor (WHO grade IV). "In glioblastoma and head and neck cancer, phosphorylated DCBLD2 recruits tumor necrosis factor receptor-associated protein 6 (TRAF6), which leads to the increased E3 ubiquitin ligase activity of TRAF6 and ubiquitin-mediated AKT activation, thereby enhancing EGFR-driven tumorigenesis." (PMID 33808696, 2021). "Moreover, DCBLD2 upregulation was associated with worse PD1 outcomes in glioblastoma (ICB_Zhao2019_PD1) and melanoma (ICB_Riaz2017_PD1 and ICB_Liu2019_PD1), worse CTLA4 outcomes in melanoma (ICB_Nathanson2017_CTLA4), and worse PDL1 outcomes in the bladder (ICB_Mariathasan2018_PDL1)." (PMID 36034778, 2022). "Our findings also revealed that high DCBLD2 expression levels were related to poorer PD1 outcomes in glioblastoma and melanoma, poorer CTLA4 outcomes in melanoma, and poorer PDL1 outcome in the bladder." (PMID 36034778, 2022). "DCBLD2 overexpression has also been reported in glioblastomas, hypopharyngeal squamous cell carcinoma, and invasive myxofibrosarcoma; however, its expression is inconsistent in different tumors." (PMID 33808696, 2021). "DCBLD2 is also upregulated in several cancers and can drive glioblastomas downstream of activated Epidermal Growth Factor Receptor." (PMID 29025973, 2017). "In glioblastomas, the membrane receptor DCBLD2 has recently shown to be a key mediator of the enhancement of (EGFR-stimulated) AKT signaling activity." (PMID 25885672, 2015). "DCBLD2 is highly expressed in patient-derived glioblastoma samples, b." (PMID 25885672, 2015). "For example, STCs exhibited, compared to STPs, the overexpression of several markers of the mesenchymal subtype of glioblastoma, such as COL1A1, COL1A2, COL5A1, IGFBP6, DCBLD2, many of which are also typically expressed by microglia or reactive astrocytes in glioblastoma microenvironment." (PMID 26188123, 2015).
melanoma (6 papers, 2010 to 2024). A malignant, usually aggressive tumor composed of atypical, neoplastic melanocytes. "In addition, DCBLD2 was associated with a poor response to PD-1 blockade immunotherapy in patients with melanoma and bladder cancer." (PMID 38339307, 2024). "DCBLD2 has been suggested to trigger oncogenic processes in melanoma through Epidermal Growth Factor Receptor (EGFR) signaling." (PMID 36894939, 2023). "In addition, DCBLD2 upregulation was related to shorter OS of melanoma and bladder cancer patients who were treated with PD1." (PMID 36034778, 2022). "DCBLD2/ESDN expression was analyzed in our (unpublished data) and other laboratories in melanoma and breast cell lines and found to be expressed only in highly metastatic cells but not in their related poorly malignant variants suggesting a positive role for DCBLD2/ESDN in tumor progression." (PMID 20525283, 2010).
breast carcinoma (3 papers, 2004 to 2022). "Furthermore, we analyzed the relationship between DCBLD2 expression level and chemotherapy sensitivity of tumor patients and found that patients with high DCBLD2 expression in Ovarian cancer and Breast cancer were less sensitive to drug therapy." (PMID 36034778, 2022). "While differential expression of the sense and antisense transcript for MMP24 was more prominent in luminal breast cancer cell lines (3/5), significant different expression levels of the DCBLD2 -SAS pair were observed solely in two luminal, hormone receptor positive breast cancer cell lines." (PMID 19615061, 2009). "In contrast, DCBLD2 and MMP24 showed significantly higher expression ratios in the solid tumours in comparison with the breast cancer cell lines." (PMID 19615061, 2009). "Furthermore the sense and antisense transcripts of DCBLD2 had different expression levels in BT474 and T47D, two hormone-receptor positive luminal-specific breast cancer cell lines." (PMID 19615061, 2009). "The 3 pairs, corresponding to discoidin, CUB and LCCL domain containing 2 (DCBLD2, NM_080927.3), matrix metallopeptidase 24 (MMP24, NM_006690.3) and keratin 81 (KRT81, NM_002281.3) had their expression interrogated in 16 breast cancer cell lines and ten solid primary breast tumours." (PMID 19615061, 2009).
colon cancer (3 papers, 2019 to 2024). "Patients with high DCBLD2 expression had a shorter survival time and a poor prognosis in the TCGA colon cancer patients receiving 5-FU treatment and the GSE17536 data set." (PMID 34095137, 2021).
gastric cancer (3 papers, 2013 to 2021). A primary or metastatic malignant neoplasm involving the stomach. "In keeping with previous data, our results suggest that DCBLD2 plays an important role in reducing tumor proliferation and metastasis in gastric cancer." (PMID 24133572, 2013).
hypopharyngeal squamous cell carcinoma (2 papers, 2021). "DCBLD2 regulates proliferation, migration, and invasion in various tumors, including glioma, hypopharyngeal squamous cell carcinoma, and myxofibrosarcoma." (PMID 33808696, 2021).
lymph node metastasis (2 papers, 2021 to 2022). "However, higher DCBLD2 expression was associated with lymph node metastasis (χ2 = 7.360, p < 0.01) and advanced TNM staging (χ2 = 6.063, p < 0.05)." (PMID 33808696, 2021). "DCBLD2 expression was higher in patients with more severe lymph node metastasis in CHOL, COAD, HNSC, KIRP, and THCA." (PMID 36034778, 2022). "The expression of DCBLD2 in protein level is positively correlated with lymph node metastasis (χ2 =7.119, p < 0.01) and TNM staging (χ2 = 6.406, p < 0.05)." (PMID 33808696, 2021). "However, DCBLD2 was significantly upregulated in patients with severe lymph node metastasis in CHOL, COAD, HNSC, KIRP, and THCA." (PMID 36034778, 2022).
Pancreatic Cancer (2 papers, 2021 to 2025). "We previously reported that DCBLD2 was overexpressed in pancreatic cancer stem cells, a small population of cancer cells with an indispensable role for tumor metastasis and recurrence." (PMID 33834039, 2021). "For pathway enrichment, DCBLD2 was mainly associated with PI3K-AKT signaling pathway, Hippo signaling pathway, Rap1 signaling pathway and pancreatic cancer in both cohorts." (PMID 33834039, 2021).
aortic stenosis (1 paper, 2022). Aortic valve stenosis is a aortic valve disease caused by the incomplete opening of the aortic valve. "Combined, these data indicate that Dcbld2−/− mice can develop CAVD with hemodynamically significant aortic stenosis, and the disease is more severe in animals with BAV." (PMID 35540096, 2022). "•The neuropilin-like protein, DCBLD2, is down-regulated in aortic valves of patients undergoing valve replacement for aortic stenosis." (PMID 35540096, 2022). "Similar to what happens in humans, a subset of TAV Dcbld2−/− mice acquires aortic stenosis, and leaflet fibrosis, calcification, and stenosis are more prevalent in BAV animals." (PMID 35540096, 2022). "Combined, these data indicate that endothelial Dcbld2 deficiency is not sufficient to promote BAV, leaflet thickening and calcification, or aortic stenosis." (PMID 35540096, 2022). "We evaluated DCBLD2 expression by immunostaining in normal human aortic valves obtained from deceased organ donors, and aortic valves with advanced CAVD obtained from patients undergoing aortic valve replacement for symptomatic aortic stenosis." (PMID 35540096, 2022).
aortic valve calcification (1 paper, 2022). "DCBLD2 expression is decreased in human CAVD, and a combination of genetic background, i.e., DCBLD2 deficiency, and BAV promotes aortic valve calcification and stenosis through enhanced BMP2 signaling in Dcbld2−/− mice." (PMID 35540096, 2022). "Expression of a neuropilin-like protein, DCBLD2, is reduced in human calcific aortic valve disease (CAVD)." (PMID 35540096, 2022). "Although this may be related to the absence of BAV in these animals, it is also possible that concomitant DCBLD2 down-regulation in VICs is necessary to induce aortic valve calcification and stenosis." (PMID 35540096, 2022).